XIST (X inactive specific transcript)
Diseases named in the same sentence as XIST in open-access papers (continued):
Sharing a sentence is not in itself a finding about the gene and the disease.
colorectal cancer (continued). "For example, the expression of M6A “writer” protein methyltransferase-like 14 (METTL14) is downregulated in colorectal cancer, and it has been found that XIST is downregulated by METTL14 in a YTHDF2-dependent way, which is responsible for inhibiting the growth of colorectal cancer." (PMID 36035993, 2022). "Nevertheless, the potential molecular mechanism of XIST in combination with miR‐93‐5p has not been explored in colorectal cancer." (PMID 32061057, 2020). "XIST is the competitive endogenous RNA of miR‐93‐5p to promote HIF‐1A, and then the upregulated AXL level facilitates the EMT process, migration, and proliferation of colorectal cancer." (PMID 32061057, 2020). "XIST mRNA is recognized by the m6A reading protein YTHDF2 which are further brought to be methylated by METTL14 through m6A, leading to XIST degradation, and thereby inhibits the tumorigenesis and metastasis of colorectal cancer cells." (PMID 33552994, 2020). "Recent studies showed that XIST expression is increased in colorectal cancer cells (Sun, Zhang, & Liu, 2018), while the interactions between miR‐93‐5p and XIST in colorectal cancer have no previous report." (PMID 32061057, 2020). "Interestingly, atractylenolides not only switched the expressions of XIST, miR‐30a‐5p and ROR1 within colorectal cancer cells but also significantly intensified the chemosensitivity of colorectal cancer cells (P < 0.05)." (PMID 30907503, 2019). "XIST could mediate EMT by up-regulating epithelial markers (E-cadherin and β-catenin) and down-regulating mesenchymal markers in colorectal cancer." (PMID 29752340, 2018). "XIST, MALAT1, H19, and KCNQ1OT1 were ranked in the top four prediction list of colorectal cancer." (PMID 26278472, 2015). "In addition, XIST binds to miR-137, and the enhancer of zeste homolog 2 (EZH2) is a target of miR-137 is repressed expression, which ultimately promotes tumor metastasis in colorectal cancer." (PMID 39830506, 2024). "As a competitive sponge for miR-93-5p, XIST may act as a positive regulator of HIF-1A, which in turn increased expression of AXL, and thus promoted the EMT process, as well as migration and proliferation in colorectal cancer." (PMID 39830506, 2024). "Therefore, XIST may work as a miR‐93‐5p ceRNA and modulate the level of HIF‐1A in the development process of colorectal cancer." (PMID 32061057, 2020). "XIST could engage in TGF-β-induced epithelial-mesenchymal transition (EMT) and cell invasion and metastasis in non-small-cell lung cancer (NSCLC) and colorectal cancer (CRC)." (PMID 31467637, 2019).
glioma (49 papers, 2016 to 2026). A benign or malignant brain and spinal cord tumor that arises from glial cells (astrocytes, oligodendrocytes, ependymal cells). "Since the rat glioma 101.8 tissue strain was originally obtained from female rats, tumor cells carry X chromosomes with high expression of the sex-linked XIST gene." (PMID 41009560, 2025). "LncRNA XIST was highly expressed in gliomas, and its overexpression is associated with the growth, invasion, metastasis and development of ovarian cancer." (PMID 29559853, 2018). "Similar to XIST, H19 was also found to be highly expressed in glioma-associated endothelial cells (GECs)." (PMID 30116729, 2018). "XIST inhibition also impaired GECs proliferation, migration and tube formation, which are the main processes associated with glioma angiogenesis." (PMID 28287613, 2017). "Additional lncRNAs that are implicated in glioma cell growth include XIST and POU3F3." (PMID 28423669, 2017). "These indicate that miR-29c and XIST are associated with each other in glioma cells." (PMID 28831025, 2017). "Specifically, lncRNA XIST is highly expressed in glioblastoma, knockdown of which induced by miR‐152 inhibits the growth, invasion, and migration of glioma cells and induces apoptosis." (PMID 38018594, 2023). "Among them, the lower LINC00599 expression and higher XIST expression were significantly correlated with worse survival of low-grade glioma patients." (PMID 37693314, 2023). "For instance, research has confirmed that XIST is notably increased in glioma tissues, whereas MEG3 can decrease the vitality of glioma cells and promote its apoptosis." (PMID 35847925, 2022). "XIST expression was significantly up-regulated in glioma tissues, and negatively correlated with Mir-137 expression." (PMID 36530425, 2022). "Another study showed that XIST silencing suppressed cell viability, invasion, migration, and glucose metabolism in gliomas." (PMID 34930117, 2021). "Specifically, the expression of XIST and miR-137 is significantly up- and down-regulated in glioma tissues, respectively." (PMID 33995499, 2021). "Data revealed that XIST expression was dramatically upregulated in 30 glioma tissues compared with 18 normal brain tissues, and was positively correlated with tumor grade (p < 0.05)." (PMID 34771549, 2021). "Silencing of XIST decreases tumorigenicity through the lncRNA-XIST/miR-126/IRS1/PI3K/Akt axis in gliomas." (PMID 34930117, 2021). "Overexpression of XIST promotes the proliferation of glioma cells, which can be reversed by miR-137 overexpression." (PMID 33995499, 2021). "Mechanistic investigations showed that XIST, miR-204-5p, and Bcl-2 formed a network to regulate cell progression in gliomas." (PMID 34930117, 2021). "Suppression of XIST inhibits tumor progression by reducing cell growth, invasion, and migration, as well as inducing apoptosis, which is mediated by miR-152 in gliomas." (PMID 34930117, 2021). "Another research group reported that XIST expedited cell growth and invasion, and suppressed cell apoptosis through inhibiting the radiosensitivity of gliomas by increasing CREB1 expression via sponging miR-329-3p." (PMID 34930117, 2021). "Recently, it was reported that downregulation of XIST suppressed cell growth, invasion, and migration, and accelerated apoptosis of glioma cells." (PMID 34930117, 2021). "XIST directly targeted miR-29c and inhibited miR-29c expression from amplifying glioma cell line chemoresistance to TMZ." (PMID 34316694, 2021). "XIST also has oncogenic functions in glioma; it inhibits miR-137 by acting as a sponge, thereby increasing Ras-related C3 botulinum toxin substrate 1(Rac1) expression." (PMID 33980320, 2021). "Bladder, breast, colorectal, lung, melanoma, gastric, and ovarian cancers as well as osteosarcoma and glioma are all among these cancers with aberrant expression of XIST." (PMID 34771549, 2021).
glioma (continued). "XIST, another oncogenic lncRNA with increased expression in glioma, plays a major role in regulating the cell cycle leading to increased tumor proliferation and invasion and decreased apoptosis." (PMID 34322395, 2021). "A subsequent study showed that XIST silencing suppressed glioma metastasis and angiogenesis in vivo and in vitro, which was mediated by miR-429." (PMID 34930117, 2021). "In summary, these data suggested that XIST played an important role in glioma progression, and functioned as a novel therapeutic target." (PMID 34930117, 2021). "For instance, in glioma, lncRNA XIST modulated RAC1 expression by functioning as a ceRNA of miR-137, which led to cell proliferation." (PMID 34771549, 2021). "Another study revealed that lncRNA XIST facilitates glioma tumorigenesis and angiogenesis by acting as a sponge for miR-429." (PMID 34681857, 2021). "Knockdown of XIST promoted apoptosis of glioma cells and inhibited cell proliferation, migration and invasion." (PMID 32489472, 2020). "A series of in vitro experiments were carried out to elucidate the role of XIST in glioma progression." (PMID 32489472, 2020). "Knockdown of XIST inhibited glioma cell proliferation, migration, and invasion and promoted apoptosis of glioma cells." (PMID 32489472, 2020). "A previous study demonstrated that XIST was upregulated in glioma tissues, and knockdown of XIST inhibited glioma cell migration, invasion and proliferation and promoted apoptosis of glioma cells." (PMID 32489472, 2020). "Bcl-2 expression was significantly lower in the shXIST group than in the shNC group in both U87 and U251 cells, suggesting that knockdown of XIST mediated glioma cell apoptosis via the Bcl-2 pathway." (PMID 32489472, 2020). "Knockdown of XIST inhibited glioma cell proliferation, migration, and invasion, promoted apoptosis of glioma cells, inhibited tumor growth and increased the survival time in nude mice." (PMID 32489472, 2020). "The expression levels of XIST and miR-204-5p in human NBTs and glioma tissues were evaluated by qRT-PCR." (PMID 32489472, 2020). "Both XIST and miR-204-5p expression levels were clearly related to glioma grade, and the expression of XIST was obviously negatively correlated with miR-204-5p expression." (PMID 32489472, 2020). "Because the expression level of XIST was significantly upregulated in glioma tissues, we explored the possible biological role of XIST in glioma progression." (PMID 32489472, 2020). "Knockdown of XIST has been shown to inhibit glioma cell proliferation and induce cell apoptosis as well as enhancing cell sensitivity to X-ray radiation, which is partially accordance to our results." (PMID 33228517, 2020). "In summary, our results demonstrated that XIST acts as an oncogene that is upregulated in glioma, whereas miR-204-5p was downregulated in glioma tissues and acts as a tumor suppressor gene." (PMID 32489472, 2020). "A few other studies also indicated XIST confers glioma cell oncogenic and chemoresistant behaviors by serving as ceRNAs to suppress actions of microRNAs." (PMID 30116729, 2018). "Emerging evidences have indicated that lncRNAs are correlated with glioma drug resistance, such as XIST, MALAT1, CACSC2, and H19." (PMID 29552296, 2018). "In contrast, several studies have reported the high expression of lncRNA XIST in several tumour tissues such as glioma and ovarian cancer." (PMID 29559853, 2018). "Results showed that XIST knockdown amplified TMZ-induced repression of glioma cells viability and reduced the lC50 values to 103.4 (LN229/TMZ) and 99.88 (U251/TMZ)." (PMID 28831025, 2017). "In order to investigate the function of XIST in glioma, we first evaluated the expression of XIST in 69 paired glioma tissues and PTBE tissues using real-time PCR assays." (PMID 28831025, 2017). "The results showed that XIST expression was up-regulated in glioma tissues, compared with that of the PTBE tissues." (PMID 28831025, 2017).
glioma (continued). "XIST knockdown reduced the lC50 values of both LN229/TMZ and U251/TMZ cells, indicating that XIST aggregated the chemoresistance of glioma cell to TMZ." (PMID 28831025, 2017). "In the present study, higher XIST expression was observed in glioma tissues and cell lines, which was related to poorer clinicopathologic features and shorter survival time." (PMID 28831025, 2017). "Our findings provide a novel understanding of the function of XIST/miR-29c/SP1/MGMT in the sensitivity of glioma to chemotherapy and the mechanism involved." (PMID 28831025, 2017). "Specifically, a recent study showed that XIST expression is abnormally up-regulated in glioma tissues and GSCs." (PMID 28293170, 2017). "We validated that XIST knockdown can enhance the repressive effect of TMZ on glioma cell proliferation; we then examined the effect of XIST on regulating the chemosensitivity of glioma cells to TMZ." (PMID 28831025, 2017). "We also monitored the expression levels of XIST in all five glioma cell lines, and the results showed that XIST expression was up-regulated in all the five glioma cell lines, U251, U373, LN229, U118, and LN229." (PMID 28831025, 2017). "XIST knockdown alone was sufficient to inhibit glioma cell proliferation and to amplify TMZ-induced cell proliferation inhibition." (PMID 28831025, 2017). "Overexpression of miR-137 reversed the influence of XIST deficiency on BTB permeability and glioma angiogenesis." (PMID 28287613, 2017). "The survival time of patients with glioma with high expression of XIST was shorter than that in patients with low expression of XIST (P=0.0007)." (PMID 28831025, 2017). "Our data suggest that XIST can amplify the chemoresistance of glioma cell lines to TMZ through directly targetting miR-29c via SP1 and MGMT." (PMID 28831025, 2017). "After confirming that XIST directly binds to miR-29c to regulate its expression, next, we assessed the combined effect of XIST and miR-29c on glioma cell proliferation and chemoresistance to TMZ." (PMID 28831025, 2017). "In the present study, we first evaluated the expression of XIST and its relationship with the clinical features in patient with glioma." (PMID 28831025, 2017). "Upon TMZ treatment, XIST acted on glioma cell proliferation in a dose-dependent manner, indicating the potential role of XIST in regulating the chemoresistance of glioma cell to TMZ." (PMID 28831025, 2017). "XIST expression is upregulated in glioma tissues and human glioblastoma stem cells (GSCs), while knockdown of XIST reduced cell proliferation, migration, and invasion, and induced apoptosis." (PMID 27686732, 2016). "The authors demonstrated the role of XIST in tumorigenesis by showing that the XIST-knockdown glioma cells displayed inhibited tumor growth, migration and invasion, and reduced apoptosis by regulating miR-152." (PMID 26983719, 2016). "A specific example is XIST-mediated sequestration of miR-29c in glioma, leading to increased expression of oncogenic targets such as transcription factor specificity protein 1 (SP1) and O6-methylguanine-DNA methytransferase (MGMT) and promoting tumor progression and chemoresistance." (PMID 41601966, 2026). "Interestingly, we previously discovered a close relationship between SRC‐1 and XIST in glioma studies, and we have now identified a connection between SRC‐1 and PNI." (PMID 40985319, 2025). "The authors also reported that XIST knockdown reduced glioma angiogenesis in vitro and in vivo." (PMID 37444408, 2023). "XIST also participated in the chemoresistance of glioma cells." (PMID 35592755, 2022). "Similar considerations could also be applied for glioma and colon and gastric cancer where both XIST and its positive regulator FTX seem to have an oncogenic role." (PMID 35054794, 2022). "Moreover, Rac1 is a target of the XIST-miR-137 regulatory axis, which is involved in glioma cell proliferation." (PMID 34930117, 2021).
glioma (continued). "A recent study revealed that XIST enhanced glioma cell chemoresistance to temozolomide via regulating miR-29c/SP1/MGMT axis, which could be a novel target for glioma treatment." (PMID 34930117, 2021). "Emerging evidence has shown that XIST expression was elevated in gliomas." (PMID 34930117, 2021). "Acting as a ceRNA, at least five miRNAs (e.g., miR-133a, miR-126, miR-137, miR-204-5p, and miR-329-3p) have been identified in the XIST-mediated ceRNETs that affect multiple hallmarks of glioma progression, including proliferation, apoptosis, migration, EMT, and angiogenesis." (PMID 33995499, 2021). "Through modulation of this miRNA, XIST regulates functions of glioma stem cells." (PMID 34368145, 2021). "Interestingly, through sponging miR-137, XIST regulates glioma angiogenesis by regulating FOXC1 (forkhead box C1) expression." (PMID 33995499, 2021). "Additionally, overexpression of XIST reduced radiosensitivity, while high expression of DRAIC was associated with a better prognosis of radiotherapy in low-grade glioma." (PMID 34322395, 2021). "Expression of XIST has been increased in glioma tissues and CSCs." (PMID 34368145, 2021). "XIST via interacting with miR-29c and through DNA mismatch repair pathway could modulate the chemoresistance of glioma cell to TMZ." (PMID 34178658, 2021). "Remarkably, XIST can act as oncogene or tumor suppressor depending on the human malignancies and was recently identified as a candidate in mediating glucose metabolism in glioma and contributing to cancer progression." (PMID 32714872, 2020). "In this study, XIST was identified as a possible target gene to modulate miR-204-5p in glioma." (PMID 32489472, 2020). "Therefore, in this study, we first detected the expression of XIST and miR-204-5p and their correlation in glioma tissues and normal brain tissues (NBTs)." (PMID 32489472, 2020). "XIST mediated glioma progression by targeting miR-204-5p in glioma cells." (PMID 32489472, 2020). "Knockdown of XIST suppressed the malignant behaviors of glioma cells by downregulating miR-204-5p." (PMID 32489472, 2020). "The knockdown of XIST reduces glioma angiogenesis in vitro and in vivo." (PMID 32992718, 2020). "Moreover, we discovered that XIST crosstalk with miR-204-5p mediates glioma cell apoptosis via the Bcl-2 pathway." (PMID 32489472, 2020). "Then, we determined whether XIST regulated the malignant biological behavior of glioma cells by targeting miR-204-5p." (PMID 32489472, 2020). "XIST crosstalk with miR-204-5p mediated glioma cell apoptosis via the Bcl-2 pathway." (PMID 32489472, 2020). "XIST crosstalk with miR-204-5p mediates glioma cell apoptosis via the Bcl-2 pathway." (PMID 32489472, 2020). "Our results confirmed that XIST bound to miR-204-5p in glioma cells in a site-specific manner." (PMID 32489472, 2020). "In the present study, we demonstrated that knockdown of XIST inhibited glioma cell proliferation, migration, and invasion, promoted apoptosis of glioma cells, inhibited tumor growth and extended survival time in nude mice, indicating that XIST is an oncogene in glioma." (PMID 32489472, 2020). "A mouse xenograft model was established to detect whether knockdown of XIST can inhibit glioma growth." (PMID 32489472, 2020). "XIST was also an oncogenic lncRNA in glioma, which could promote glioma tumorigenicity and angiogenesis by acting as a molecular sponge of miR-429 and maintenance of GSCs via miR-152." (PMID 31052326, 2019). "LncRNA CASC2 was reported to be identified as a glioma suppressor gene via miR‐21, while lncRNA XIST is an oncogene that acts as a molecular sponge of miR‐429.39, 40 Among numerous kinds of nonprotein‐coding RNAs, lncRNAs have a key regulatory role in cancer biology." (PMID 30924320, 2019). "XIST inhibited miR-29c expression by direct targeting in TMZ-resistant glioma cells." (PMID 29556138, 2018).